IL23R (interleukin 23 receptor)
Diseases named in the same sentence as IL23R in open-access papers (continued):
Sharing a sentence is not in itself a finding about the gene and the disease.
Crohn disease (continued). "We studied association of single-nucleotide variants in IL23R with IBD in Swedish patients, in both Crohn's disease (CD) and ulcerative colitis (UC) subsets." (PMID 19175939, 2009). "Genomic DNA from 2670 Caucasian individuals including 833 patients with Crohn's disease (CD), 456 patients with ulcerative colitis (UC), and 1381 healthy unrelated controls was analyzed for 10 IL23R SNPs." (PMID 17786191, 2007). "Furthermore, novel avenues are being explored in the domain of IL-23+ Tregs therapy, namely the generation of IL-23R-specific CAR Tregs for the management of Crohn’s disease, and the delineation of the role of Tregs in the pathogenesis of cancer." (PMID 39796684, 2024). "A previous study has reported IL23R as a gene associated with inflammatory bowel disease (IBD), whereby nine SNPs in IL23R at various locations such as intronic, exonic and UTR have shown significant associations with Crohn’s disease." (PMID 36232773, 2022). "Those diseases that are classified toward the autoinflammatory end of the spectrum, such as Crohn’s disease, have a strong IL-23R component, whereas those that are deemed primarily autoimmune in their course of pathogenesis, such as T1D and MS, are not generally associated with IL-23R." (PMID 30054427, 2018). "While IL23R is well known to be associated with Crohn’s disease this reported interaction is not previously studied." (PMID 26369336, 2015). "We found that IL23R (L310P) variant conferred a protective effect for crohn’s disease (CD) but not ulcerative colitis (UC) patients." (PMID 25159710, 2014). "Hence, we aimed to examine the association between IL23R (L310P) and ATG16L1 (T300A) polymorphisms and inflammatory bowel disease (Crohn’s disease and Ulcerative colitis) in a cohort of Moroccan patients." (PMID 25159710, 2014). "Additionally, the mRNA and protein expression of JAK2 and IL-23R were increased in UC and Crohn's disease (CD) patients." (PMID 24382939, 2013). "The upregulation of the IL23R in CRC is of interest in view of previous reports on significantly elevated mucosal levels of IL23R mRNA in Crohn's disease and more recent reports linking an IL23R polymorphism to the development of inflammatory bowel diseases, typically with an increased risk of CRC." (PMID 22173670, 2012). "Moreover, IL23R+ intestinal T-cell populations expand in Crohn’s disease and associate with anti-TNF non-response." (PMID 41154835, 2025). "There are exceptions with odds ratios of 3.9 and 2.5 reported for variants of NOD1 and IL23R on the risk of inflammatory bowel disease (IBD) while the distribution of effect sizes for the remaining 69 variants associated with Crohn's disease ranged from 1.04 to 1.74." (PMID 23982303, 2014). "Intestinal mucosa and PBMC lnc-ITSN1-2, IL-23R, and inflammatory cytokines were measured in 120 IBD patients [60 Crohn's disease (CD) and 60 ulcerative colitis (UC)] and 30 HCs." (PMID 32547537, 2020). "These pathways involve key cytokines and signal transducers, such as IL-23R, IL-12B, IL-21, IL-4, and IL-5, in psoriatic arthritis; IL-23R, IL-12B, IL-13, Rel, TYK2, and JAK2 in Crohn's disease." (PMID 32161545, 2020). "In addition, epistasis between IL23R and other Th17 related genes has been reported: with IL2/IL21 in UC and with IL17A and IL17RA in Crohn's disease." (PMID 22359581, 2012). "In fact, our findings were well correlated with the report about GSE111761 that in patients with Crohn’s disease receiving anti-TNF therapy, there were significant upregulations of mucosal Il-23p19, Il23R and Il17A in non-responders, but not in responders." (PMID 33193322, 2020).
inflammatory bowel disease (82 papers, 2007 to 2026). A spectrum of small and large bowel inflammatory diseases of unknown etiology. "Genetic studies further support the pivotal involvement of IL-23 in disease pathogenesis, demonstrating that variants in the IL23R gene are significantly associated with susceptibility to inflammatory bowel disease (IBD)." (PMID 41426578, 2025). "Recent genome-wide association studies (GWAS) identified that IL-12B and IL-23R are susceptibility genes for inflammatory bowel disease (IBD)." (PMID 36430241, 2022). "A strong association between the incidence of inflammatory bowel diseases and an important controller of microbial infiltration, the interleukin-23 receptor (IL23R) gene, has been reported." (PMID 35456757, 2022). "The clinical relevance of the IL-12/IL-23 signalling pathway to gut inflammatory disease has been well established, and a coding variant in the IL-23R gene has been strongly associated with the susceptibility to inflammatory bowel disease (IBD)." (PMID 32580776, 2020). "IL-23R gene variants also play an essential role in the development of many autoimmune diseases such as ankylosing spondylitis (AS), inflammatory bowel disease (IBD), and systemic lupus erythematosus (SLE)." (PMID 26090488, 2015). "One of the most significant is the interleukin 23 (IL-23) pathway, highlighted by associations within the IL23R (interleukin 23 receptor, alpha chain) gene region to inflammatory bowel disease (IBD), psoriasis, and ankylosing spondylitis." (PMID 22715389, 2012). "Genome-wide association studies have also identified multiple single nucleotide polymorphisms (SNPs) in the IL23R gene region associated with inflammatory bowel diseases." (PMID 22984500, 2012). "A genome-wide association study has revealed that polymorphisms of the IL23R gene are associated with inflammatory bowel disease (IBD)." (PMID 21151597, 2010). "Association of the interleukin-23 receptor (IL23R) with inflammatory bowel disease (IBD) has been confirmed in several populations." (PMID 19175939, 2009). "Whether IL-23R, as a gene associated with inflammatory bowel disease, can also affect the brain development of children by affecting intestinal flora remains to be seen." (PMID 33324152, 2020). "Previous studies showed that IL-23R rs1884444 variation is associated with susceptibility to esophageal and gastric cancer, schistosomiasis-associated immune reconstitution inflammatory syndrome, and inflammatory bowel disease." (PMID 28427357, 2017). "Importantly, genome wide association studies in human inflammatory bowel disease also suggest a prominent role of the innate immune system and of IL-23R variants in defining susceptibility to disease." (PMID 24586521, 2014). "Genome-wide association studies have demonstrated highly significant associations between polymorphisms in IL-23 pathway genes, notably IL-23R, to a number of chronic inflammatory disorders, including inflammatory bowel disease (IBD), psoriasis, and ankylosing spondylitis." (PMID 23469228, 2013). "Mutations in the IL23R gene are linked to inflammatory bowel disease susceptibility." (PMID 20732640, 2010). "However, the relevance of IL-23 in human disease is highlighted by the finding that polymorphisms within the IL23R gene locus are linked to susceptibility to the two forms of inflammatory bowel disease (IBD), Crohn's disease (CD), and ulcerative colitis (UC)." (PMID 18400195, 2008). "The study of IL‐23R and IL‐17RA isoforms in periodontitis is important because it has been determined that some IL‐23R gene variants (G149R, R381Q, and V3621) are associated with protection in patients with inflammatory bowel disease, while other variants increase their susceptibility." (PMID 41536464, 2026). "The hypomorphic variant rs11209026-A in the IL23R gene provides significant protection against immune-related diseases in Europeans, notably inflammatory bowel diseases (IBD)." (PMID 39923740, 2025).
inflammatory bowel disease (continued). "The susceptible alleles of IL-23R are also related to psoriatic arthritis (PsA) and inflammatory bowel disease (IBD)." (PMID 40002719, 2025). "Recent genome-wide association studies identified IL12B and IL23R as susceptibility genes for inflammatory bowel disease (IBD)." (PMID 22479607, 2012). "The IL23R gene has been identified as a susceptibility gene for inflammatory bowel disease (IBD) in the North American population." (PMID 17786191, 2007). "Given the critical role of IL-23R signaling and IL-23R-expressing mucosal cells in the development of ﻿inflammatory bowel diseases, targeting IL-23R using CAR-T cells represents a promising therapeutic strategy." (PMID 40959055, 2025). "The IL-23/IL-23R pathway has also been shown to impact the function of type 1 regulatory T cells in patients with inflammatory bowel disease, resulting in a reduction in IL-10 production." (PMID 39796684, 2024). "IL23R is a well-established disease-susceptibility gene for inflammatory bowel disease (IBD)." (PMID 33165574, 2021). "Inflammatory bowel diseases (IBD) are characterized by inflammatory conditions in the digestive tract and are associated with an increase in IL-23R signaling, able to promote tumor growth." (PMID 34680190, 2021). "This has been previously reported in human IL23R in which a SNP within IL23R was protective against inflammatory bowel disease." (PMID 28807314, 2017). "The contribution of IL-23R to inflammatory bowel diseases has been explored in various mouse models of colitis, sometimes demonstrating a protective role and other times exacerbating disease." (PMID 24586521, 2014). "Knockout mice deficient in either p40/p19 or subunit of the IL23 receptor (IL23R and IL12R-β1) develop less severe symptoms of multiple sclerosis and inflammatory bowel disease highlighting the importance of IL23 in the inflammatory pathway." (PMID 25614713, 2014). "The IL23R protective (A) allele and the NOD2 (C) risk allele rs2066845 were associated with a positive family history of inflammatory bowel disease." (PMID 23300620, 2012). "Notably, IL23R is a well-known susceptibility locus for inflammatory bowel disease (IBD)." (PMID 41026325, 2025). "In addition, specific splice variants of IL12B and IL23R have been linked to disseminated BCG infection and with inflammatory bowel disease." (PMID 26861902, 2016). "In addition to being a major susceptibility gene in inflammatory bowel disease (‘IBD’), IL23R is also involved in the pathogenesis of other autoimmune diseases, such as psoriasis and ankylosing spondylitis, implicating common proinflammatory pathways in these diseases." (PMID 26375822, 2015). "The Inflammatory Bowel Disease (IBD) Panel, which includes NOD2, IL23R, and ATG16L1 genes along with CYP2C19, which are associated with IBD severity and susceptibility can aid in defining genetic risk and tailoring treatment for patients suffering from Crohn’s disease and ulcerative colitis." (PMID 38420192, 2024). "The role of IL-12 and IL-23 signaling in the development of IBD is highlighted by the fact that patients with complete loss-of-function mutations in IL23R, IL12RB1, or IL12B do not develop spontaneous inflammatory bowel disease." (PMID 39795980, 2024). "Association of genetic markers in the interleukin-23 receptor (IL23R) gene, and the intergenic region between IL23R and IL12RB2, with inflammatory bowel disease (IBD) was first identified in 2006." (PMID 19175939, 2009). "LncITSN1-2 has been demonstrated that it promotes IBD CD4+ T cell activation, proliferation, and Th1/Th17 cell differentiation by serving as a ceRNA for IL-23R via sponging miR-125a in inflammatory bowel disease (IBD)." (PMID 35812382, 2022).
inflammatory bowel disease (continued). "Similarly, HS intake in mice resulted in an enhanced inflammatory response in terms of cytokine production (pro-inflammatory TNF-α, IL-17A, and IL-23), increased IL-23R+CD4 T cells, MAP, and exacerbated colitis in mice with artificially induced inflammatory bowel disease (IBD)." (PMID 37108475, 2023).
autoimmune disease (52 papers, 2010 to 2025). A disorder resulting from loss of function or tissue destruction of an organ or multiple organs, arising from humoral or cellular immune responses of the individual to their own tissue constituents. "The clinical relevance of IL-23R is considerable, with variants in this gene having been associated with an increased risk of developing autoimmune diseases." (PMID 39796684, 2024). "Later, the results of various studies showed that a single nucleotide polymorphism (SNP) in IL-23R gene is linked to several human autoimmune diseases, indicating that IL-23 signaling is an essential event in the development of pathogenic Th17 cells." (PMID 32582147, 2020). "Several variants in the IL-23R gene have been reported for their associations with human autoimmune disorders, such as psoriasis and inflammatory bowel disease." (PMID 27893410, 2016). "Recently, the mechanisms of IL-23R variants have been investigated in different autoimmune diseases." (PMID 26090488, 2015). "Further analysis of the clinical features and the IL23R polymorphisms suggested that rs17375018 was strongly associated with AS concomitant with uveitis which is an autoimmune disease." (PMID 23840727, 2013). "In these studies several independent signals located within IL23R locus were suggested; however, only the R381Q (rs11209026) polymorphism, whose minor allele plays a protective role for several autoimmune disease, appear to have a functional involvement." (PMID 24312163, 2013). "We decided to investigate for the first time the possible role of different STAT4/IL23R autoimmune disease-associated polymorphisms on the susceptibility to develop non-anterior uveitis and its main clinical phenotypes." (PMID 24312163, 2013). "Recently, studies have shown that some single nucleotide polymorphisms (SNPs) of the IL23R gene are strongly associated with several autoimmune diseases, such as Crohn’s disease, rheumatoid arthritis, AS, and Behcet’s disease." (PMID 23840727, 2013). "The present study adds to an increasing number of reports of IL-23R importance in susceptibility to autoimmune diseases." (PMID 21253534, 2010). "Notably, the investigation of IL23R polymorphism primarily gained momentum within the realm of autoimmune diseases." (PMID 37464360, 2023). "Here, in agreement with the causal role of IL23 signaling in autoimmune diseases, GWAS and fine-mapping experiments suggest that strategies that directly inhibit the IL23 receptor (IL23R) could be of even greater potential therapeutic value." (PMID 33798443, 2021). "Since then, genetic variants of IL-23R have been investigated in numerous autoimmune diseases." (PMID 26678098, 2015). "Numerous cells express IL‐23R on their surface, including dendritic cells (DCs), macrophages, and polarized lymphocytes, and hence IL‐23 operates in a variety of cells and is associated with the progression of diseases such as tumors, infections, and autoimmune disorders." (PMID 37647444, 2023). "Pathogenic Th17 cells, with higher expression of Il17, Csf2, Il23r, and Il1r1, play a pivotal role in the pathogenesis of autoimmune disorders." (PMID 37716986, 2023). "Studies suggest an important role of IL-23 receptor (IL-23R) in the pathogenesis of autoimmune diseases including CD." (PMID 35203496, 2022). "IL23 signaling through the IL23R promotes the proliferation, maintenance, and activation of Th17 inducing neutrophil inflammation and autoimmune diseases." (PMID 32437414, 2020). "Top SNPs shared between RA and CD, as well as RA and UC or UC and CD, lie in regions well-known to be shared across multiple autoimmune diseases, such as the HLA, IL23R, TNFAIP3, and IL2RA." (PMID 29309429, 2018). "Regarding IL23R, the statistical power of our study to detect the described odds ratios in previous GWASs on different autoimmune diseases was higher than 80%, considering the strong effect sizes observed in those studies for the analyzed IL23R variants." (PMID 24312163, 2013).
autoimmune disease (continued). "Th17 cells that support autoimmune disease are characterized by increased expression of cytokines including IL-33, surface markers including IL-23R and transcription factors including T-bet." (PMID 23844143, 2013). "The results of our study confirmed the relevance of the IL-23/IL-17 axis in the pathogenesis of SLE and further highlighted the importance of IL-23R+ T cell subsets in this autoimmune disease." (PMID 21110900, 2010). "Our studies support future research either in the production or clinical trials of therapeutic antibodies targeting IL-23/IL-17 axis receptors in SLE, particularly IL-23R, and the inhibition of IL-23/IL-17 receptors is a promising therapeutic strategy in this autoimmune disorder." (PMID 34484186, 2021). "IL-23R signaling is known to induce pathogenic Th17 cells in autoimmune diseases, while non-pathogenic Th17 cells are induced by TGF-β." (PMID 31253169, 2019). "However, IL-23 signaling through the IL-23 receptor (IL-23R) increases IL-17A production and is important in pathogenesis of autoimmune diseases and potentially asthma." (PMID 31849948, 2019). "IL-23R deletion reduces Th17 cells and ameliorates autoimmune diseases in Act1−/− mice, implicating the importance of hyper Th17 cells (with increased STAT3 activation and IL-21 expression) for the autoimmune diseases associated with Act1 deficiency." (PMID 30013031, 2018). "Our results do not support a relevant role, similar to that described for other autoimmune diseases, of IL23R and STAT4 polymorphisms in the non-anterior uveitis genetic predisposition." (PMID 24312163, 2013). "Furthermore, IL-23R has now been proposed as a common genetic marker for a variety of autoimmune diseases." (PMID 22262980, 2012). "IL-23R has now been proposed as a common genetic marker for a variety of autoimmune diseases." (PMID 22262980, 2012). "However, similar to STAT4, other IBD susceptibility genes such as IL23R, IL2/IL21, STAT3, and PTPN2 are associated with other autoimmune diseases." (PMID 20454450, 2010). "In animal models of autoimmune diseases, proinflammatory cytokines IL-1β and IL-23 have been shown to be enhancers and stabilizers of partially or completely differentiated effector Th17 cells, which dominantly express corresponding receptors for these cytokines, IL-1R1 and IL-23R." (PMID 32582147, 2020). "An IL-23R-mediated altered response to IL-23 signals in γ/δ cells can lead to overproduction of IL-17, suggesting a potential mechanism that increasing IL-23R expression might play a role in the human autoimmune disease." (PMID 27902482, 2017). "However, there was no epistasis between PTPN2 and IL23R, although both genes predispose to autoimmune diseases." (PMID 22457781, 2012). "In addition to the therapeutic potential of IL23p40 in autoimmune diseases, as demonstrated in our study, targeting a functional IL23R-CHR in IL23 receptor complex could also provide a useful route for ameliorating IL23/IL17-involved inflammatory diseases." (PMID 23029144, 2012). "IL23R has an impact on the activity of NK and especially Th17 cells and may participate in acute response to infection in peripheral tissues as well as in certain autoimmune diseases, like morbus Chron." (PMID 22253695, 2012). "In addition to the IL-23A gene, some genes related to the IL-23A functions also have been investigated for their possible associations with the risk of autoimmune diseases, such as the variant rs10889677 in the IL-23R gene associated with MS (consensus not reached yet)." (PMID 27893410, 2016). "Additionally, a great number of SNPs were found to affect IL23R, a receptor involved in IL23A signaling that is known to be related to AS as well as some autoimmune diseases, and has been previously studied as a possible therapeutic target." (PMID 40507438, 2025).
autoimmune disease (continued). "The IL23R gene, a receptor of key immunoregulatory cytokine with pro-inflammatory properties, became one of the most non-HLA candidate genes in several organ-specific autoimmune diseases." (PMID 38605394, 2024).